ZBED5 (zinc finger BED-type containing 5)
Synonyms: Buster1
Tractability: PROTAC: ubiquitination databases record sites on it.
Gene: Protein-coding gene on chromosome 11 (10,812,074 to 10,858,796, reverse strand). Ensembl gene ENSG00000236287.
Subcellular location (Human Protein Atlas): Golgi apparatus; Nucleoli fibrillar center; Nucleoplasm
Gene Ontology:
Molecular function: DNA binding
Genetic constraint (gnomAD): Loss-of-function variants: 29 observed, 51.08 expected, observed/expected ratio (o/e) 0.57, 90% interval 0.42 to 0.77. The upper end of that interval is the gene's LOEUF score, 0.77, which puts it in group 3 of 6, group 1 being the genes least tolerant of losing a copy. Missense variants: 775 observed, 851.64 expected, observed/expected ratio (o/e) 0.91, 90% interval 0.86 to 0.97. Synonymous variants: 281 observed, 308.77 expected, observed/expected ratio (o/e) 0.91, 90% interval 0.82 to 1.
Homologues: Orthologues: chimpanzee ZBED5 (99% identical), dog ZBED5 (98% identical), pig ZBED5 (98% identical), macaque ZBED5 (96% identical), guinea pig ZBED5 (93% identical). Paralogues in human: SCAND3 (34% identical), ZBED11 (29% identical), ZBED8L (27% identical), ZBED8 (27% identical), EPM2AIP1 (18% identical), THAP12 (10% identical), ZMYM4 (10% identical), ZMYM2 (9% identical), ZMYM3 (9% identical), GTF2IRD1 (8% identical), ZMYM6 (8% identical), ZMYM1 (7% identical), and 6 more.
Diseases named in the same sentence as ZBED5 in open-access papers:
ZBED5 is named in the same sentence as 1 disease in open-access papers, as found by Europe PMC text mining. Sharing a sentence is not in itself a finding about the gene and the disease. The quoted sentences say what the papers report.
cancer (1 paper, 2024). A tumor composed of atypical neoplastic, often pleomorphic cells that invade other tissues. "Furthermore, an analysis of the relationship between infiltration estimation and gene expression in gene modules revealed that T-cell CD4+ Th1 in genes ERRFI1, ZBED5, UQCRC2, ZNF146, ABHD17A, YWHAZ, and especially PLSCR4 showed a negative correlation in nearly 40 types of cancer." (PMID 38464509, 2024).